CD68 (CD68 molecule)
Diseases named in the same sentence as CD68 in open-access papers (continued):
Sharing a sentence is not in itself a finding about the gene and the disease.
tumor (continued). "The tumor-infiltrating lymphocytes (TILs) in the central and peripheral regions of the tumors were analyzed separately using markers including CD20, CD3, CD68, CD8, CD4, CD163 and FOXP3." (PMID 39198311, 2024). "Within primary tumor, CD163+ was positively correlated with CD163+MMP9+ (r = 0.751, P = 0.0013) and CD68+CD163+CD206+ (ρ = 0.762, P = 9.7E−4)." (PMID 39373616, 2024). "Immunohistochemically, the tumor cells commonly express CD117, mast cell tryptase, CD13, CD33, CD43, and CD68." (PMID 39404971, 2024). "Immunohistochemistry was used to evaluate the expression of PD-L1 and tumor microenvironment cells (CD4, CD8, CD68 and CD163)." (PMID 39123373, 2024). "The number of CD8+ cytotoxic T cells, as well as CD68+ and CD163+ macrophages, differed significantly between the invasive front and the tumor center." (PMID 39630300, 2024). "Our results showed that, compared to the vehicle group, probenecid treatment increased the number of CD68‐positive cells and IBA1‐positive cells in the tumor core area and the border area." (PMID 38948951, 2024). "The second panel identified CK+ tumor/epithelial cells, CD8+ cytotoxic T cells (Tc), CD8− T cells, and CD68+ macrophages, as well as the expression of PD-1 and PD-L1 on these cells." (PMID 39510069, 2024). "The findings of this study provide compelling evidence that elevated expression levels of CD47, CD68, and CD163 in tumor tissues are significantly correlated with poorer PFS and OS in patients with NPC." (PMID 39682556, 2024). "As spatial proteomics based in IHC methods such as seqIF retain the best markers for tissue region (PanCK: Tumor, SMA: Stroma, CD31: vessel, etc.)and cell (CD4: t-cell, CD68: Macrophage, CD56: NK cell, etc.)identification." (PMID 38473208, 2024). "Tissues were stained for pan-cytokeratin (panCK; tumor epithelium), caspase-1, CD3 (lymphocytes), CD8 (CTL), CD68+ (monocytes/macrophages), and CD163+ (M2-like, protumoral TAMs)." (PMID 39353903, 2024). "Tumor biopsies obtained during surgery were analyzed for expression of NCF2, CYBB, CD68, CD163, and NCAM1 by RT-PCR." (PMID 38598844, 2024). "Specifically, we examined the presence of CD4+, CD8+, CD20+, CD68+, and CD163+ cells within the tumor microenvironment." (PMID 38288307, 2024). "The results showed that tumor-immune cell regions trended toward expressed SMA, HLA-DR, CD68 and CD4 proteins similarly to the THC regions." (PMID 39499374, 2024). "This study investigates the prognostic impact of the omega-6/omega-3 ratio and tumor infiltration by CD8+ lymphocytes and CD68+ macrophages on overall survival (OS) and disease-free survival (DFS) in NSCLC patients undergoing pulmonary resection." (PMID 39330005, 2024). "In general, surface markers such as CD68 and CD80 show anti-tumor effects, while CD163 and CD204 show tumor-promoting effects." (PMID 39199574, 2024). "The role of tumor-infiltrating immune cells, particularly CD8+ T cells and CD68+ macrophages, has been established as a significant factor in the prognosis of various cancers, including NSCLC." (PMID 39330005, 2024). "We examined CD4, CD8, CD68 and CD163 cells for analysis of the tumor microenvironment in both intratumoral and stromal compartments, as well as the overall number of tumor microenvironment cells." (PMID 39123373, 2024). "Histopathological examination of the resected tumor revealed typical features of RDD, including large histiocytes, lymphocyte infiltration, and immunohistochemical positivity for CD68, S-100, and Vimentin." (PMID 39678509, 2024). "The positive rate of CD4, CD45RO, and CD68 was higher, while the positive rate of CD20, CD27 and CD8 was lower in tumor tissues than those in corresponding non tumor tissues, which was coincident with the result of immune infiltration analysis." (PMID 38532632, 2024).
tumor (continued). "Five clusters of PanCK positive tumor cells were identified: PanCK positive, PanCK/PD-L1 double positive, PanCK/PD-L1/CD33 triple positive, PanCK/CD33/FOXP3 triple positive, and PanCK/CD68/CD33/PD-L1/FOXP3 positive." (PMID 38898200, 2024). "Baseline expression of CD8, CD68, CD163, PD-1, PD-L1 and regulatory T cells (Treg) in the tumor microenvironment was evaluated with clinical outcome." (PMID 38339307, 2024). "The results indicated a statistically significant increase in the number of tumor‐infiltrating T cells (CD3+, CD8+), CD68+ macrophages, and CD11c+ macrophages after NACT." (PMID 38778559, 2024). "Multiplex IHC staining of five different immune cell markers (CD8, CD68, FOXP3, PD1, and PD-L1) confirmed the validity of inferring tumor immune microenvironment features from a multiomics dataset." (PMID 39482530, 2024). "Immunostains revealed the tumor cells to be positive for CD31, CD68, CD163, and CD34 (focal), whereas CD8 and CD 21 were negative." (PMID 38824259, 2024). "Multiplex immunohistochemistry and multispectral imaging was used to evaluate tumour infiltration of cytotoxic T cells (CD8+), Th1 cells (T-bet+), T regulatory cells (FoxP3+), B cells (CD20+), and macrophages (CD68+) in a cohort of 257 CRC patients." (PMID 38040818, 2024). "In conclusion, our study underscores the significance of functional status and spatial interaction of CD68+SHP2+ TAMs, particularly within the tumor region." (PMID 38799432, 2024). "The infiltration density of CD68+TAMs and CD4+FoxP3+Tregs in the tumor area of Mφ-Siglec-15+PD-L1+ patients were higher than that of Mφ-Siglec-15−PD-L1− patients (p < 0.05)." (PMID 38072971, 2024). "All patients with the immune-high subtype exhibited more than three immune clusters within the tumor, which were characterized by CD20-positive B cells surrounded by a high number of CD3-positive T cells, and rare cells positive for CD68 and/or CD163." (PMID 38611048, 2024). "Compared to sham control mice, the CD45hi/CD11bhi compartment significantly expands in tumor-bearing mice and exhibits a myeloid-specific signature composed of VISTA, CD80, PD-L1, CTLA-4, MHCII, CD40, and CD68." (PMID 39123357, 2024). "High immune infiltration means more tumor infiltrating immune cells, so we stained CD3, CD4, CD8, CD20, CD68 to measure the immune infiltration status." (PMID 37593098, 2023). "To assess the association of Siglec-15 expression with tumor-infiltrating macrophages, we analyzed the gene expression levels of Siglec-15 and tumor-infiltrating macrophage markers (CD68 and CD163) in 31 types of tumor tissues from the TCGA and GTEx databases." (PMID 37234161, 2023). "The CD68+ and CD163+ cells were more abundant in the tumor than DCs and found both in the tumor epithelium and in the tumor stroma around the neoplastic glands." (PMID 37435060, 2023). "The tumor was positive for CD31, CD34, D2-40, CD68, Ki-67 (1% to 2% positive nuclear staining) immunomarkers as well for the smooth muscle markers SMA and desmine." (PMID 37297823, 2023). "Tumor tissues from HCC patients were probed with anti-ALDOA, anti-CD68, anti-CD163, anti-CD4 and anti-FOXP3 antibodies." (PMID 36937389, 2023). "Since the number of GCs in GC tumour of the bone is determined by other factors like RANK-L, CD68-expression confirms their differentiation as osteoclast-like GCs of a monocyte origin." (PMID 37509363, 2023). "It uses multiplexed immunofluorescence for the simultaneous visualization and quantification of CD68 + macrophages, CD8 + T cells, FOXP3 + regulatory T cells, PD-L1/PD-1 protein expression, and tumor cells." (PMID 36959234, 2023). "In the tumor nest, both CD64+CD68-CD163- and CD64+CD68+CD163- TAM were detected, while CD64+CD68+CD163+ TAM were concentrated within the tumor stroma and the peritumoral area, mostly in the T-cell enriched area." (PMID 37691949, 2023). "Tumor sections were stained with CSC biomarkers (CD44, c-Myc, EpCAM) and macrophage biomarkers (F4/80, CD68)." (PMID 37553567, 2023).
tumor (continued). "As expected, density of the immunophenotypic features in tumour compartments was lower than in stromal compartments, and density was the highest for CD3 and CD68." (PMID 37419892, 2023). "The data showed that SIGLEC15, CD68 and CD163 gene expression was broadly upregulated in tumor tissues compared with normal tissues." (PMID 37234161, 2023). "In a CD68-associated pan-cancer analysis, CD68 was found to be highly expressed in many cancer types and associated with immune infiltration in tumor mutation burden (TMB), microsatellite instability (MSI), and TME, which may become a new immune checkpoint in future tumor immunotherapy." (PMID 37880277, 2023). "There was an upward trend of CD68+ macrophage and PD‐1+ and CTLA‐4+ tumor cells in the involved lymph nodes of R compared to C." (PMID 36751105, 2023). "The TME status was pathologically examined by CD3, CD68, and CD20 staining of resected tumor slides." (PMID 37400504, 2023). "The mean nearest distance (MND) between CD68/CD163 subsets and T cells to tumor cells in HNSCC or keratinocytes in control tissue was determined as another distance and density correlate." (PMID 38322012, 2023). "The tumor was highlighted with CD10, showed focal positivity with actin, desmin, and CD68, and had increased Ki67 immunohistochemical staining." (PMID 38247725, 2023). "We observed that CD14+, CD68+, and CD163+ monocytes and CK+ tumor cells predominantly expressed LAIR-1 more than other cell types." (PMID 36960400, 2023). "The cell density of CD68/CD163 subsets varied between 0.2 and 0.7% (tumor nests and squamous epithelium, respectively) and 0.2 - 6.8% (stroma)." (PMID 38322012, 2023). "In contrast, CD68+IRF8+, CD68+CD163+CD206+ macrophages were less enriched in both tumor and stroma regions." (PMID 37723144, 2023). "As expected, CD68, CD86, CD206, and Arg-1 levels were more significant in tumor tissues than in ANT." (PMID 38264642, 2023). "We observed that MFAP5 + fibroblasts mainly infiltrated fibroblast areas that were close to M2-phenotype macrophages (marked by CD68 and CD163) but opposite to anti-tumor T cells or B cells." (PMID 37344903, 2023). "After determining the tumor cells by desmin, marking intact glandular tissue with cytokeratin 7 (CK7) and excluding macrophages by CD68, the distribution and localization of GALNT14 was investigated." (PMID 37671061, 2023). "T-lymphocytes (CD3, CD4, CD8) and macrophages (CD68, CD163) were also present in tumour cell areas (iTILs) (B + D)." (PMID 36726072, 2023). "The focus of this study was to evaluate the relationships between the spatial localization and function of cell subsets distinguishable by CD68 and CD163 and their functional roles in the HNSCC tumor microenvironment." (PMID 38322012, 2023). "Tumor cell segments also display higher expression of CD8, CD11c, CD56, CD68, and CD127, indicating an enriched immune infiltration comprising of cytotoxic T-cells, antigen-presenting cells such as DCs and macrophages near tumor cell segments." (PMID 38044986, 2023). "Furthermore, the patients with a high CD8 + mTILs/CD68 + TAMs ratio gained a major benefit from adjuvant trastuzumab, suggesting that the inflammatory conditions in the tumor microenvironment may influence the efficacy of trastuzumab, but further studies addressing this question are needed." (PMID 37428418, 2023). "Each cluster was identified as GBM tumor cells or macrophages based on the expression of SOX2 and CD68, respectively (Fig EV1B and C)." (PMID 37791581, 2023). "After 15 days of treatment, E-cadherin, CD68, and CD8 were increased, while vimentin, STAT3, NF-κB, CD163, and CD25 were reduced (as detailed in Table Expression, B and 8 A) in tumours of Balb/c mice when compared to the control group." (PMID 36857852, 2023). "In the BLT-derived GBM8 tumor, human immune cells were detectable, with CD56+ NK cells (0.29%), CD11c+ DCs (0.11%), CD68+ macrophages (0.08%), and T lymphocytes (0.12%) constituting the immune landscape." (PMID 38274817, 2023).
tumor (continued). "The results confirmed that BCL2A1 was positively correlated with this series of tumor-related macrophage markers, especially CCL2 and CD68." (PMID 37889551, 2023). "It is important to emphasize in this context, that beside T cells, also the CD68/CD163 subsets and tumor cells expressed PD-1 to some extent." (PMID 38322012, 2023). "The present study shows that the spatial distribution of CD4+, CD8+, CD68+, and CD163+ immune cells differs between the tumor center and invasion front of OSCC." (PMID 36836239, 2023). "The cell density of the thus defined CD68/CD163 subsets, CD45+ leukocytes and keratinocytes or HNSCC (CK+) in squamous epithelium or tumor nests and stroma was then determined." (PMID 38322012, 2023). "In our study, we detected 17 immune-related markers inside the tumor of HCC patients, then we found CD44, CD20, CD68, HLA-DR, and CD31 as the prognosis-related markers using LASSO Cox regression model." (PMID 38223688, 2023). "Two patients with partial response had higher SIA, derived from cell counts considering complement co-expression by CD68+CD163+ macrophages, in comparison to one patient with tumour progression." (PMID 36724681, 2023). "We evaluated tumor portion (nuclear grade, necrosis, BAP-1, MSLN) and TME portion (CD4, CD8, CD20, CD68, elastic fibers collagen type I and type V fibers) by quantitative digital analyses." (PMID 37901248, 2023). "But a significantly better mOS (high tumor infiltration CD68+ macrophages vs. low tumor infiltration CD68+ macrophages cases, 26 vs. 15 months, P = 0.002) was observed in BRAF wide-type mCRC with higher tumor infiltration CD68+ macrophages." (PMID 37302081, 2023). "When overlaying gene expression of CXCL9, CD3D (t cells) and CD68 (macrophages), we see moderate spatial correlation with CXCL9 and CD3D (r = 0.4, p = 3E-29) along the tumor-stromal interface, and weaker correlation with CD68 (r = 0.17, p = 1E-10)." (PMID 36906603, 2023). "Lymphocyte infiltration and the expressions of different proteins on tumor cells (CD56, CD15, CD68, and ph-mTOR) were analyzed." (PMID 37190322, 2023). "Phenotypes (Tumor - CK+, Cytotoxic - CD3+CD8+, Tregs - CD3+FOXP3+, Macrophages - CD68+, Other- T cells – CD3+CD8-) were characterized using the lineage and functional markers." (PMID 38179056, 2023). "We were able to find only one study describing the co-localization of CD68 and SPP1 in tumor stromal components in human CRC." (PMID 36895491, 2023). "Comparison exhibited that patients with both high expression of HBx and CD68 were more often had MVI and a larger tumor size (both P < 0.01)." (PMID 37370037, 2023). "Among 22 GC patients who received immunotherapy at PUMCH, patients with high expression of CD68 and CD163 in tumour tissues had a lower ORR." (PMID 37199594, 2023). "Within all leukocytes (CD45+ leukocytes and CD68/CD163 subsets combined), CD45+ leukocytes generally had the highest cell density relative to total cell density (16.0 - 45.5% in tumor nests or squamous epithelium and 85.2 - 96.2% in stroma)." (PMID 38322012, 2023). "MIF assays were performed to examine immunological marker expression levels, including CD8, CD68, CD163, PD-L1, and PD-1, in the tumor, stroma, and total region." (PMID 38023213, 2023). "The presence of tumor-infiltrating lymphocytes (TILs) expressing CD3, CD8, CD68, PD-L1 (detected by antibody SP142) and FOXP3 at primary and metastatic LN sites was quantified." (PMID 36892732, 2023). "Next, we performed a Kaplan–Meier analysis of the groups with a high and low number of CD68-, CD163-, and CD204-positive macrophages in both tumor areas." (PMID 36690825, 2023).
tumor (continued). "A peculiar feature of the mTDLN was the presence of peritumoral aggregates of CD20+ B cells in close contact with the tumor itself and with CD64+CD68+ and CD64+CD68- peritumoral TAM." (PMID 37691949, 2023). "It should be noted in this analysis, included studies evaluate the expression of CD68+ TAM in more than one area (stroma and tumour (intra-tumoural) area)." (PMID 37397243, 2023). "As concerns macrophages, we observed an increased number of CD68+CD163+ and CD68+IDO1+ cells in MUC1H tumor samples, revealing that TAMs were M2-polarized and able to produce KYN." (PMID 36902242, 2023). "Enrichment of T-cell markers (CD3, CD4), macrophage markers (CD68, CD168), immune checkpoints (CD27 and V-domain Ig suppressor of T-cell activation [VISTA]), CD44 and CD45 were seen in the stroma relative to the tumour." (PMID 37835491, 2023). "We subsequently evaluated if there is a correlation between spatial distribution of CD68/CD163 subsets, T cells and tumor cells to clinical outcome parameters." (PMID 38322012, 2023). "The correlation factor between invasion front and tumor center for CD4+ lymphocytes, CD8+ lymphocytes, CD68+ macrophages, CD163+ M2-macrophages and M1-macrophages were 0.3841, 0.6587, 0.5831, and −0.0658 respectively." (PMID 36836239, 2023). "In human breast tumors, CD68+ and CD163+ macrophages were significantly increased at the invasive front compared to the tumor core, and macrophages at the invasive tumor front positively correlated with tissue stiffness." (PMID 37296891, 2023). "Immunosuppressive cells and tumor cells both gathered at a relatively short distance, and CD68+ CD163+ macrophages (tumor-promoting M2 macrophages) were diffusely distributed within tumor cores and located close to tumor cells after PD-L1 blockade." (PMID 37488287, 2023). "To characterize immune populations within the tumor microenvironment, we evaluated the expression of CD3, CD4, CD8, FOXP3, and CD68." (PMID 36672477, 2023). "The number of tumor infiltrating immune cells as determined by CD45 and CD68 counts showed an overall decrease during the first eight fractions, however not statistically significant." (PMID 37572156, 2023). "Immunohistochemistry for CD68 (a pan-macrophage marker) and CD163 (a specific M2 macrophage marker, M2 macrophages are thought to facilitate tumor growth) was comparable between patients <40 years, 40–65 years, and >65 years." (PMID 37568649, 2023). "YUMMER1.7 tumor tissue was collected at endpoint and used for immunohistochemical staining to analyze CD3, CD8, CD68 and CD163 positive cells in the tumor." (PMID 37964379, 2023). "In the tumor center and in the tumor periphery, the CD68+CD86+MRP8-14neg M1, CD68+CD163+ CD206neg M2, and CD68+CD206+CD163neg M2 macrophage subtypes were far from the MCs." (PMID 37637998, 2023). "The higher expression of CD68, CD163, CD206 on CD45/CD14+ cells in the 4-culture PANC-1 spheroids suggest a monocytes differentiation into M2-like macrophages, known to have tumor supporting functions." (PMID 37519820, 2023). "This has important clinical relevance since the authors also demonstrated a strong correlation between Notch1 and immunosuppressive cells such as CD68+CD163+TAMs and immune checkpoint molecules in patient HNSCC tumor samples." (PMID 38269089, 2023). "To address how Q11 affects cancer cells through macrophages, we performed the immunohistochemical staining for CD68 (macrophage marker) and CD163 (M2 marker) on tumor tissue slices." (PMID 37875398, 2023). "The CD68+, CD68+CD163+, and CD68+CD163+CD206– macrophages were abundant in both tumor and stroma regions." (PMID 37723144, 2023). "In the tumor compartment, patients with PR had higher expression of ER-alpha, PD-L1, Pan-AKT, CD68, Ki-67, and Fibronectin, but lower expression of CD44, CD127, CD34, and VISTA." (PMID 37153589, 2023). "Next, we determined what proportion of PD-1-expressing T cells had contact with PD-L1-expressing CD68/CD163 subsets and tumor cells." (PMID 38322012, 2023).